AQP1 (aquaporin 1 (Colton blood group))
Diseases named in the same sentence as AQP1 in open-access papers (continued):
Sharing a sentence is not in itself a finding about the gene and the disease.
lung carcinoma (30 papers, 2008 to 2025). "AQP1 expression has been linked to angiogenesis and tumor migration in different types of cancer, including lung cancer, in in vivo and in vitro experiments." (PMID 36142499, 2022). "AQP1 may be implicated in lung cancer cell invasion and migration, which AQP1-shRNA able to inhibit." (PMID 38336645, 2024). "In another study using AQP1 deficient mice, both breast and lung cancer progression was evaluated." (PMID 30555637, 2018). "By modulating AQP-1 water channel activity and protein expression in the Lewis lung cancer model, acetazolamide is eventually beneficial as an angiogenesis antagonist." (PMID 38336645, 2024). "Silencing AQP1 through siRNA significantly decreased the expression levels of MMPs in lung cancer cells with varying AQP1 expression levels." (PMID 39440058, 2024). "In a separate study, it was revealed that AQP1 upregulation in the capillary endothelium of lung-carcinoma and mesothelioma tumours encouraged angiogenesis, hence promoting the development and propagation of cancer." (PMID 38336645, 2024). "AQP1 promotes angiogenesis in lung cancer, and elevated levels of AQP1 expression were related with significant postoperative metastases and poor disease-free survival rates." (PMID 38336645, 2024). "An investigation revealed that the subcellular location of increased AQP1 expression in the vascular endothelium of lung cancer capillary endothelial cells were accountable for angiogenesis." (PMID 38336645, 2024). "AQP1 has also been reported to promote the proliferation and migration of lung cancer cells in vitro and has been considered as a prognostic marker in lung adenocarcinoma." (PMID 36246134, 2022). "In terms of individual molecules, most of them were studied in human cancers, including lung cancer (e.g., AQP1, AQP4, IL33, and PEBP4)." (PMID 35211471, 2022). "A decreased overall survival of cutaneous melanoma patients has been linked to a positive AQP1 expression, and an increased AQP3 expression in skin cancer patients and lung cancers has been detected." (PMID 36233821, 2022). "A down-regulation of AQP1 has been reported in lung cancer cell lines treated by combination therapy of celecoxib and afatinib." (PMID 33807998, 2021). "Previous studies have demonstrated that AQP1 was overexpressed in lung cancer in vitro and in vivo, and upregulation of AQP1 was related to worse prognosis." (PMID 34708074, 2021). "Transfection of AQP1 into lung cancer cells enhanced proliferation in vitro; AQP1 overexpression in capillary endothelia of lung adenocarcinoma and mesothelioma tumors promoted angiogenesis, which would facilitate cancer growth and spread." (PMID 32679804, 2020). "In lung cancer cells, AQP1 knockdown had inhibitory effects on cancer cell proliferation and migration along with the downregulation of MMP‐9 expression." (PMID 32253832, 2020). "It has been suggested that AQP1 is involved in lung cancer differentiation and in the pathophysiology of inflammatory bowel disease." (PMID 31533210, 2019). "In lung cancer AQP1 plays a role in promoting angiogenesis and the expression levels of AQP1 was correlated with high postoperative metastasis and low disease-free survival rates." (PMID 30555637, 2018). "The over-expressed AQP1 was located in the endothelial cells of capillaries within lung cancer tissue responsible for the development of angiogenesis." (PMID 25886458, 2015). "We have previously demonstrated the expression of AQP1 in human primary lung cancer tissues; 18 out of 44 samples of non small cell lung cancer patients showed positive AQP1 protein expression." (PMID 18478076, 2008). "In conclusion, it can be proposed that AQP1 may promote the proliferation and migration of lung cancer cells in a manner dependent on MMP-2 and MMP-9120." (PMID 39440058, 2024). "Cell proliferation was increased in vitro when AQP1 was transfected into lung cancer cells." (PMID 38336645, 2024).
lung carcinoma (continued). "Moreover, RNA interference-mediated silencing of AQP1 was observed attenuate the proliferation and metastasis of lung cancer cells." (PMID 39440058, 2024). "initially reported the expression of AQP1 in resected lung cancer samples." (PMID 35847914, 2022). "In lung cancer it is common to see overexpression of AQP1, AQP3, AQP4, and AQP5." (PMID 30555637, 2018). "AQP1 was up-regulated in lung adenocarcinoma and inhibition of AQP1 expression can inhibit tumor cell invasion, which thereby were proposed as the prognostic index and therapeutic target for lung cancer." (PMID 25886458, 2015). "It was proposed that AQP1 could be a significant prognostic index for stage and histologic differentiation of lung cancer." (PMID 25886458, 2015). "Furthermore, AQP1 and -4 expression was highly correlated across the 105 lung cancer and normal samples (Pearson correlation: 0.82) as previously observed in the microarray data." (PMID 21548930, 2011). "AQP1 could regulate lung cancer cell invasion and migration which can be inhibited by AQP1-shRNA." (PMID 25886458, 2015). "Researchers revealed that AQP1 siRNA inhibited MMP2 and MMP9 expression in LTEP-A2 and LLC lung cancer cell lines." (PMID 38336645, 2024). "For instance, hypomethylation has been observed in the oncogenes AQP1, LINE-1, and ELMO3 in salivary gland adenoid cystic carcinoma, colorectal cancer, and lung cancer, respectively." (PMID 38399367, 2024). "A hypomethylation status has been reported for several oncogenes, including AQP1 in salivary gland carcinoma, LINE-1 in colorectal cancer, and ELMO3 in lung cancer." (PMID 37175004, 2023). "A significant reduction in the migration of AQP1 shRNA and AQP4 shRNA cells was observed compared to control lung cancer cells." (PMID 38681779, 2023). "In the case of lung cancer, although AQP3 is expressed in the normal respiratory tract and plays an important role in the maintenance of water homeostasis, similar to AQP1, expression of AQP3 also participates in pulmonary carcinomatosis." (PMID 35847914, 2022). "In pathological conditions, AQP1 is required for the MMP2- and MMP9-dependent migration of lung cancer cells in vitro." (PMID 35163313, 2022). "Expression of AQP1, AQP3, and AQP5 was negatively associated with the degree of cellular differentiation, and higher expressions of AQP1 and AQP5 were observed among invading lung cancer cells with metastasis." (PMID 35847914, 2022). "A later follow-up study reported that AQP1, AQP3, and AQP5 were detected in 71%, 40%, and 56% of resected lung cancers, respectively." (PMID 35847914, 2022). "Overexpression of AQP1, AQP3 and AQP5 has been the major focus of papers published in the lung cancer field." (PMID 32679804, 2020). "The high expression of AQP1 and FYN in lung cancer tissues increased the possibility of them as true targets of miR-146a-5p." (PMID 31285693, 2019). "The progression of breast and lung cancer was studied in mice lacking AQP1; in contrast to animals with normal AQP1 expression, tumour mass, vascular integrity, and lung invasion were reduced." (PMID 38336645, 2024). "AQP1 and AQP5 play important roles in lung pathophysiology and disease, including chronic and acute lung injury, COPD (COPD), other inflammatory lung diseases, and lung cancer." (PMID 37180448, 2023). "AQP1 and FYN were validated by RT-qPCR to be potential targets of miR-146a-5p in lung cancer." (PMID 31285693, 2019). "AQP1, AQP3, AQP4 and AQP5 are over-expressed in lung cancer." (PMID 25886458, 2015). "In our previous findings with AQP1 in lung cancer, no notable morphologic changes in AQP1 transfected cells were reported." (PMID 18478076, 2008). "Hence, the expression of AQP1 and FYN tend to be inversely modulated by miR-146a-5p in lung cancer." (PMID 31285693, 2019). "Currently, we found that two likely miR-146a-5p targets, AQP1 and FYN, showed higher levels in tissues obtained from lung cancer, compared to noncancerous lung tissues." (PMID 31285693, 2019).
colorectal cancer (22 papers, 2008 to 2025). A primary or metastatic malignant neoplasm that affects the colon or rectum. "Previous studies found that colorectal cancer mainly expresses AQP1, 3 and 522, but barely expresses AQP823." (PMID 32576929, 2020). "It has also been observed that overexpression of AQP1 not only increases plasma cell membrane permeability by approximately 41% in colorectal cancer cells, and consequently promotes cell migration." (PMID 29104239, 2017). "Specially, AQP1, AQP3 and AQP5 expression has been demonstrated in seven human colon and colorectal cancer cell lines, and they are associated with an early stage of colorectal cancer development." (PMID 27589719, 2016). "AQP1 expression was higher in advanced mammary and colorectal carcinomas where AQP1 immunoreactivity was also seen in some neoplastic tumor cells." (PMID 24338153, 2014). "AQP1, AQP3, AQP5, and AQP9 are associated with colorectal cancers; among them, it has been indicated that AQP5 promotes the proliferation and metastasis of CRC; moreover, elevated expression of AQP5 in CRC tissue is associated with a poor prognosis of colorectal cancer." (PMID 36114463, 2022). "In addition, AEBP1 is upregulated in vascular endothelial cells and promotes tumor angiogenesis in colorectal cancer by inducing angiogenesis-related genes like AQP1." (PMID 34692770, 2021). "AQP1, AQP3, AQP5, and AQP9 all have roles associated with colorectal cancer." (PMID 30555637, 2018). "Downregulation of AQP1 may be a potential therapeutic goal to minimize cell migration for colorectal cancer patients." (PMID 30555637, 2018). "So downregulation expression of AQP1 in colorectal cancer may be a new therapeutic approach." (PMID 25886458, 2015). "Underexpression of AQPs for AQP8 has been observed in colorectal cancer, AQP8 and AQP9 in hepatocellular carcinoma, AQP4 in pleural mesothelioma, and AQP1 in cervical cancer." (PMID 40100646, 2025). "The expression and functions of AQP1 and AQP5 have been the main focus of papers published in the colorectal cancer field." (PMID 32679804, 2020). "Within this final set, the largest proportion of studies addressed AQP1, followed by AQP5, AQP4, AQP3 and AQP9, for a diverse array of cancer types, including brain, lung, breast and colorectal cancers." (PMID 32679804, 2020). "AQP1, AQP3, AQP5, AQP8 and AQP9 play a clinically relevant role in hepatic cancer as they do in colorectal cancer." (PMID 30555637, 2018). "Based on these preliminary findings and prior observations we had with AQP1 in NSCLC and AQP5 in colorectal cancer study, we have examined the expression profile of AQP5 in a large panel of clinical samples." (PMID 18478076, 2008).
glioblastoma (22 papers, 2002 to 2024). The most malignant astrocytic tumor (WHO grade IV). "Intriguingly, the upregulated genes after AQP1 overexpression were strongly associated with glioblastoma, as indicated by the top disease ranking, suggesting a potential involvement of AQP1 in tumorigenesis." (PMID 38057925, 2023). "Among the enrichment results for the upregulated DEGs, we observed that glioblastoma ranked as the top disease in the disease category, suggesting the overexpression of AQP1 in the C6 cell line strengthened the expression of genes associated with glioblastoma." (PMID 38057925, 2023). "AQP1, in particular, has been linked to rapid invasion and migration characteristic of aggressive cancers such as glioblastoma." (PMID 34769339, 2021). "In this study, we analyzed the role of AQP1 overexpression in glioblastoma and elucidated the main mechanisms involved." (PMID 38057925, 2023). "The effects of pharmacological compounds on glioblastoma invasion were assessed individually and in combination with the AQP1 water channel inhibitor AqB013 in assays using transwell filters with extracellular matrix." (PMID 36831372, 2023). "AQP1 channels promote invasion of glioblastoma tumor cells through the ECM and into surrounding tissues." (PMID 36831372, 2023). "An experiment displayed enhanced AQP1 production after exposure to hypoxia in rat glioblastoma cells; AQP1 expression was correlated with the degree of glycolysis and this finding suggested that AQP1 generation is stimulated by hypoxia-induced glycolysis." (PMID 36077720, 2022). "The ADC has been proposed as a biomarker of AQP gene expression, as earlier studies have demonstrated that the ADC obtained with high b values was correlated with the amount of increasing expression of AQP1 in glioblastoma cell lines." (PMID 32413082, 2020). "Hayashi and colleagues observed enhanced AQP1 expression by hypoxia in 9L rat glioblastoma cells which correlated with the extent of glycolysis, and postulated that AQP1 expression is induced by hypoxia-facilitated glycolysis." (PMID 28146084, 2017). "AQP1 is up-regulated in different carcinomas including: colon, breast, lung and glioblastoma multiforme." (PMID 27409610, 2016). "AQP1 is strongly expressed in several human breast carcinomas, glioblastoma multiformes and several types of primary lung tumors." (PMID 27409610, 2016). "To gain further insight into the consequences of Aqp1 induction by hypoxia, we performed experiments in 9L cells, a glioblastoma cell line in which up-regulation of Aqp1 mRNA by hypoxia has also been reported." (PMID 22174795, 2011). "AQP1 mRNA levels have recently been shown to be increased in human glioblastoma, compared with normal human brain." (PMID 12237771, 2002). "Aqp1 was also detected in endothelial cells in glioblastoma transplanted into mouse brain." (PMID 38474310, 2024). "Concurrent inhibition of AQP1 augmented the block of invasion in glioblastoma, indicating channels could serve complementary roles in facilitating motility." (PMID 36831372, 2023). "Transcriptional and protein expression studies in a human brain specimen showed that AQP1 is overexpressed in astrocytomas, and there is emerging evidence for a correlation between AQP1 expression levels and histological grades of astrocytoma with glioblastoma showing the highest AQP1 expression." (PMID 36768856, 2023). "Roles of the AQP1 dual water-and-ion channels in glioblastoma remain to be explored." (PMID 34769339, 2021). "AQP1, 4, 8, and 9 are highly expressed in glioblastoma cell lines." (PMID 28555065, 2017). "To evaluate AQP1 as a genetically encoded reporter for diffusion-weighted MRI, we used lentiviral transfection to generate CHO, U87 glioblastoma and Neuro 2a neuroblastoma cell lines stably overexpressing this channel, and corresponding control cells expressing a green fluorescent protein (GFP)." (PMID 28008959, 2016).
glioblastoma (continued). "We tested the hypothesis that glioblastoma cell invasiveness can be controlled by the combined pharmacological inhibition of AQP1 and ion channels known to be upregulated in GBM." (PMID 36831372, 2023). "Pellets of AQP1- and GFP-expressing CHO, U87 glioblastoma and Neuro 2a neuroblastoma cells were then imaged using DWI." (PMID 28008959, 2016). "McCoy and Sontheimer reported that most primary cell cultures of glioblastoma did not express the water channels AQP-1, 4 and 5, but in vivo they did." (PMID 22590566, 2012). "In that study, AQP1 immunoreactivity was found in glioblastoma cells and microvascular endothelial cells, but not normal brain parenchyma or normal microvessel endothelium." (PMID 12237771, 2002). "Results showed antagonists of AQP1, Na+, K+, and Ca2+ channels; Ca2+-activated K+ channels; and AMPA/kainate-type glutamate receptors, and an agonist of metabotropic glutamate receptors, are promising targets for the optimization of small-molecule inhibitors of glioblastoma tumor motility." (PMID 36831372, 2023).
pulmonary edema (21 papers, 2013 to 2026). Accumulation of fluid in the lung tissues causing disturbance of the gas exchange that may lead to respiratory failure. "The findings from the current study indicate that the altered expression of AQP1 in FES may be associated with the development of pulmonary edema." (PMID 27455237, 2016). "The present study indicated that AQP1 water transport dysfunction may be a predominant cause of pulmonary edema in acute lung injury, however, further studies are required to provide further confirmation." (PMID 25009607, 2014). "Therefore, the expression level of AQP-1 is associated with pulmonary edema." (PMID 25371738, 2014). "In another study, AQP1 levels were examined in newborn lamb models that replicated infant CPB with hypothermic circulatory arrest, and an increase in AQP1 mRNA levels was detected, suggesting a possible relationship with pulmonary edema." (PMID 41010898, 2025). "Correspondingly, following the administration of the three anti-asthmatic drugs, despite a reduction in pulmonary edema, there was an increase in the mRNA and protein expression of AQP1 and AQP5." (PMID 39440058, 2024). "According to studies, AQP1 and AQP5 are involved in the development of pulmonary edema caused by ALI." (PMID 36820212, 2023). "Our results showing that AQP1 mRNA is differentially expressed in mice exposed to Cl2 are consistent with these findings and imply AQP1 role in the fluid infiltration (pulmonary edema) and respiratory distress that follows exposure to Cl2." (PMID 36246134, 2022). "The severity of pulmonary edema formation is judged by the D/W ratio and the protein expressions of AQP-1 and AQP-5." (PMID 35123524, 2022). "Another study using an ALI mouse model focusing on the expression of AQP1, AQP3, AQP4 and AQP5 suggested AQP1 and AQP5 to play important roles in the abnormal fluid transport in ALI and their association with the development of pulmonary edema." (PMID 33673336, 2021). "At the same time, inhibition of AQP1 decreased the pathological damage resulting from pulmonary edema." (PMID 27455237, 2016). "Previous studies have identified that in hyperoxic lung injury-induced pulmonary edema mice models, the expression level of AQP1 in lung tissues was significantly downregulated." (PMID 25009607, 2014). "Previous studies have confirmed that aquaporin 1 (AQP1) and AQP5 expressions were positively related to the severity of pulmonary oedema and inflammation, while antiasthmatic treatment could reduce asthma by increasing the levels of AQP1 and AQP5." (PMID 41280738, 2025). "A study on mice with lungs infected with adenovirus demonstrated that AQP-1 and -5 expressions could decrease the occurrence of pulmonary oedema by reducing vascular permeability to the lung interstitium." (PMID 35151337, 2022). "Previous studies show that the AQP1 level varies inversely with the degree of pulmonary edema." (PMID 33362540, 2020). "A change in either AQP1 or AQP5 expression may represent a response to inflammation-associated pulmonary edema, and it may be causal in the formation of pulmonary edema." (PMID 27455237, 2016). "The expression of AQP1 in the lung is decreased in a viral infection model of pulmonary edema." (PMID 27455237, 2016). "Downregulation of AQP1 expression in alveolar microvessels may act as a compensatory mechanism to protect against the formation of excessive pulmonary edema (PE) in chronic heart failure." (PMID 25705683, 2015). "Decreased lung AQP1 and AQP5 expression may be associated with pulmonary edema development and increased severity of lung injury and pulmonary edema, which may provide an additional mechanism for pancreatitis-associated lung injury." (PMID 25009607, 2014). "Studies have shown that AQP1 may be important in lung fluid transportation, as well as in the pathogenesis of pulmonary edema." (PMID 25009607, 2014).